KLK10 (kallikrein related peptidase 10)
Description:
Has a tumor-suppressor role for NES1 in breast and prostate cancer.
Synonyms: NES1; PRSSL1
Tractability: Antibody: UniProt places it where antibodies can reach, with high confidence; its Gene Ontology location is reachable by antibodies, with high confidence; UniProt predicts a signal peptide or a membrane-spanning region.
Gene: Protein-coding gene on chromosome 19 (51,012,739 to 51,021,048, reverse strand). Ensembl gene ENSG00000129451.
Subcellular location: Secreted
Gene Ontology:
Molecular function: serine-type endopeptidase activity; serine-type peptidase activity
Biological process: protein maturation; proteolysis
Cellular component: extracellular region; secretory granule
Genetic constraint (gnomAD): Loss-of-function variants: 29 observed, 23.59 expected, observed/expected ratio (o/e) 1.23, 90% interval 0.91 to 1.67. The upper end of that interval is the gene's LOEUF score, 1.67, which puts it in group 6 of 6, group 1 being the genes least tolerant of losing a copy. Missense variants: 386 observed, 336.25 expected, observed/expected ratio (o/e) 1.15, 90% interval 1.05 to 1.25. Synonymous variants: 173 observed, 139.01 expected, observed/expected ratio (o/e) 1.24, 90% interval 1.1 to 1.41.
Homologues: Orthologues: chimpanzee KLK10 (99% identical), pig KLK10 (83% identical), macaque KLK10 (82% identical), dog KLK10 (82% identical), guinea pig KLK10 (76% identical), rat Klk10 (68% identical), mouse Klk10 (67% identical), zebrafish habp2 (26% identical), zebrafish f9a (26% identical), tropical clawed frog cfi (24% identical), Drosophila melanogaster CG31266 (21% identical), Drosophila melanogaster CG31267 (18% identical). Paralogues in human: CFD (30% identical), F12 (30% identical), KLKB1 (29% identical), F11 (28% identical), F7 (28% identical), HGFAC (28% identical), C1R (28% identical), PRSS55 (26% identical), F9 (26% identical), C1S (25% identical), C1RL (24% identical), F10 (24% identical), and 4 more.
Diseases named in the same sentence as KLK10 in open-access papers:
KLK10 is named in the same sentence as 76 diseases in open-access papers, as found by Europe PMC text mining. Sharing a sentence is not in itself a finding about the gene and the disease. The quoted sentences say what the papers report.
breast carcinoma (31 papers, 2001 to 2026). "In silico analysis of 400 HER2-positive breast cancer patients of the TCGA dataset revealed a positive association between the KLK10 mRNA expression and a worse patient outcome." (PMID 36294951, 2022). "In fact, KLK10 also has been found related to the prognosis of breast cancer due to its association with tamoxifen resistance." (PMID 27825132, 2016). "Importantly, high KLK10 expression was associated with poor prognosis of breast cancer, indicating that KLK10 is a potential target and prognosis predictor for trastuzumab resistance." (PMID 27825132, 2016). "Therefore, it would be interesting to explore whether plasma level of KLK10 are associated with drug resistance and overall survival in breast cancer." (PMID 27825132, 2016). "This particular upregulation of KLK10 expression in TNBC suggests a functional involvement of this protease in the tumor biology of this breast cancer subtype." (PMID 36294951, 2022). "Further evidence of the decrease of KLK10 mRNA expression in breast cancer tissues was discovered by in situ hybridization analysis." (PMID 35669967, 2022). "In 1996, the KLK10 was characterized as a possible tumor suppressor gene, and its expression was reduced in a breast cancer cell line." (PMID 35669967, 2022). "A previous study by Luo and colleagues analyzing the prognostic potential of KLK10 in breast cancer disclosed a correlation between high KLK10 antigen levels in tumor tissue and a higher risk of disease recurrence as well as cancer-related death." (PMID 36294951, 2022). "Other genes were associated with cell adhesion and migration of breast cancer cell [DUOXA1 and PGAM1], prognosis of breast cancer [PGK1 and KLK10], or clinical outcome in breast cancer [RBM3 and AQP5]." (PMID 34497807, 2021). "KLK10 exon 3 methylation correlated to high disease grade (breast cancer), late stage (lung cancer) and bad patient prognosis (acute lymphoblastic leukemia)." (PMID 29690914, 2018). "High expression of KLK10 was related to poor prognosis in HER2 positive breast cancer patients (n = 434, log-rank p = 0.0165418)." (PMID 27825132, 2016). "In summary, by co-expression analysis of TCGA data with gene expression profile of trastuzumab resistant breast cancer, we identified KLK10 as a potential biomarker and intervention target for trastuzumab resistance." (PMID 27825132, 2016). "Given the significant effect of drug resistance on clinical outcome, we explored the relevance of KLK10 expression to the overall survival of breast cancer patients." (PMID 27825132, 2016). "KLK5, for instance, was reported to be downregulated in breast cancer, whereas elevated expression of KLK6, KLK7 and KLK10 has been associated with multiple cancers and poor prognosis in gastric and colorectal cancer." (PMID 29263803, 2016). "The normal epithelial cell-specific-1 (NES1) gene, also named as KLK10, is recognised as a novel putative tumour suppressor in breast cancer, but few studies have focused on the function of KLK10 in human prostate cancer." (PMID 26616394, 2015). "Recently, Band and colleagues have shown, using in situ hybridisation, lower levels of KLK10 expression in breast cancer cells when compared to normal cells." (PMID 14710225, 2004). "KLK10 (also known as the normal epithelial cell-specific 1 gene, NES1) appears to be a novel tumour suppressor, which is down-regulated during breast cancer progression." (PMID 12439720, 2002). "Interestingly, our results show that SCGB3A1‐Epi and KLK10‐Epi are key drivers of liver metastasis in breast cancer and PDAC, respectively." (PMID 40357856, 2025). "Interestingly, the overall KLK10 mRNA expression in breast cancer (encompassing all subtypes) in comparison to healthy tissue was lower, which is in line with the findings of other studies." (PMID 36294951, 2022).
breast carcinoma (continued). "In addition to the prognostic value and solid expression in breast cancer, KLK10 has been identified to be an important factor contributing to tamoxifen and trastuzumab resistance, suggesting it as a potential new therapeutic target." (PMID 36294951, 2022). "In breast cancer cells, androgens were shown to synergistically enhance estrogen-dependent expression of KLK10 and KLK11 indicating that coordinate expression of KLK10 and KLK11 may rely on hormone-dependent regulatory mechanisms as well." (PMID 29095848, 2017). "Interestingly, KLK10 is a proposed tumor suppressor gene in breast carcinoma cell lines, blocking tumorigenicity in an in vivo breast cancer model." (PMID 26231762, 2015). "In addition, KLK10 (NES1) was identified from breast cancer cells but is down-regulated in the progression of EOC." (PMID 24043563, 2014). "The overall expression of KLK10 and KLK11 in TNBC in comparison to the other KLKs was assessed using the publicly available TCGA breast cancer dataset." (PMID 36294951, 2022). "MiR-8073 binds to at least five mRNAs (FOXM1, MBD3, CCND1, KLK10, and CASP2) in various cancers such as colon, pancreatic, and breast cancer in vitro and determines the gene and protein expression levels of these five targets." (PMID 35163589, 2022). "KLK10, also known as normal epithelial cell-specific 1 (NES1), is a member of the KLK family with a molecular weight of 30 kDa and was originally reported as a tumor suppressor in breast cancer cells." (PMID 28418926, 2017). "A previous study showed that high levels of KLK10 (also known as the normal epithelial cell-specific 1, NES1) in tumor tissue predicted tamoxifen resistance in breast cancer patients." (PMID 24043563, 2014). "For example, human kallikrein (KLK) 10 (normal epithelial cell specific-1; NES1) and KLK 14 are reported to be downregulated in breast cancer." (PMID 15611789, 2005). "In our studies of prognostic value of various kallikrein in cancer, we found down-regulation in breast cancer of KLK14 and in testicular cancer of KLK10." (PMID 11986781, 2002). "Specific ligand‐receptor interactions were observed between these epithelial subtypes and fibroblasts, with significant interactions between CD74‐APP receptors in SCGB3A1‐Epi and Fib‐11 in breast cancer and between SPP1‐CD44 receptors in KLK10‐Epi and Fib‐11 in PDAC." (PMID 40357856, 2025). "KLK10 mRNA as well as antigen expression levels were found to be downregulated in breast cancer tissue, compared to non-cancerous breast tissue, however, the specific regulatory mechanism has not been clarified yet." (PMID 36294951, 2022). "However, as shown in the present paper, KLK10 expression was significantly elevated in the TNBC subtype, not only compared to the other breast cancer subtypes, but also to healthy tissue." (PMID 36294951, 2022). "Altogether, KLK10 and KLK11 may have the potential to serve as prognostic biomarkers, and represent possible targets for therapy in breast cancer." (PMID 36294951, 2022). "On the other hand, KLK-mediated degradation of extracellular matrix proteins facilitates tumor cell invasion and metastasis, and higher serum levels of other kallikreins such as KLK5, KLK10, and KLK14 have been found in women with breast cancer when compared to healthy ones." (PMID 32344524, 2020). "The gene product (KLK10) is a secreted protein found in normal human mammary epithelial cells (MECs) but downregulated or absent in the majority of human breast cancer cell lines." (PMID 29690914, 2018). "Furthermore, our data strongly indicate co-expression of KLK10 and KLK11 on the mRNA level in advanced ovarian cancer, which has already been observed in non-small-cell lung and breast cancer." (PMID 29095848, 2017).
breast carcinoma (continued). "Although previous studies have demonstrated the crucial role of KLK10 and KLK11 in breast cancer patients’ relapse, disease progression and shorter survival rates, a potential role for the KLK gene family in lymph node metastasis was first proposed in the present study." (PMID 26311227, 2015). "In particular, sensitivity of IgYs for detection of endogenous KLK6 and lack of crossreactivity with other KLKs and unrelated proteins was assessed by analyzing whole cell lysates and supernatants isolated from MDA-MB-468 breast cancer cell line that expresses the KLK5, KLK6 and KLK10 proteins." (PMID 23216878, 2012). "With respect to breast cancer in particular, several kallikrein family members, namely KLK3, KLK5, KLK6, KLK10, KLK12, KLK13, and KLK14 were shown to be differentially expressed at the mRNA or protein levels within the cancerous tissues or serum of such patients." (PMID 16434994, 2006). "Indeed, tumor-specific lack of KLK10 expression correlated to KLK10 exon 3 hypermethylation in a majority of cell lines and in primary breast cancer." (PMID 29690914, 2018). "Interestingly, the results obtained for KLK14 in this study are comparable to those obtained for KLK3, KLK6 and KLK15 in breast cancer and KLK4, KLK5 and KLK10 in ovarian cancer, in that high expression of these kallikrein genes also correlated with patient prognosis." (PMID 12439719, 2002).
ovarian carcinoma (25 papers, 2002 to 2024). A malignant neoplasm originating from the surface ovarian epithelium. "In case of ovarian cancer, Luo and co-workers revealed that high serum levels of KLK10 were significantly associated with serous epithelial type, late-stage, advanced grade tumors, suboptimal debulking, and no response to chemotherapy." (PMID 29095848, 2017). "Reports have shown diagnostic and prognostic uses of KLK10 in ovarian cancer, and as such, it represents a possible therapeutic target for metastatic ovarian cancer." (PMID 20354523, 2010). "Recently, KLK10 was identified as a potential target for immunotherapy based on the immunopeptidome analysis of ovarian cancer antigens." (PMID 37938164, 2023). "Peritoneal metastasis is more frequent and abundant in ovarian cancer where the expression of certain members (KLK6 and KLK10) of the KLK family in ascitic fluids from ovarian cancers has been reported." (PMID 35883559, 2022). "KLK10 protein levels in tumor tissue have been described as an independent, unfavorable prognostic marker not only for late-stage ovarian cancer, but also for other types of cancer." (PMID 29095848, 2017). "Concerning the other two analyzed KLKs, prior studies have indicated that KLK10 is elevated in ovarian cancer, with highest levels observed in tumors of more advanced stage." (PMID 29095848, 2017). "Expression of miR-224, let-7f and miR-516a is decreased in ovarian cancer, and they synergistically regulate expression of kallikrein-related peptidase 10 (KLK10)." (PMID 23667495, 2013). "KLK10 was identified as a putative tumour suppressor in breast and gastric cancers, and is often silenced in ovarian cancer cell lines and tumours, despite its expression in the serum being an unfavorable prognostic marker." (PMID 22102857, 2011). "The positive and dominant effects of KLK10 on overall survival make it an attractive putative therapeutic agent for ovarian cancer." (PMID 22102857, 2011). "Herein we report the first attempt to unravel the contributions of KLK5, 6 and 10 in a xenograft model of ovarian cancer, and the first therapeutic use of a recombinant KLK10 protein in vivo." (PMID 22102857, 2011). "Kallikrein-related peptidase 10 is a member of the kallikrein family that has been shown by numerous reports to be up-regulated in ovarian cancer." (PMID 20354523, 2010). "The KLK10, which is documented to be up-regulated in ovarian cancer by many independent reports, was chosen for experimental validation of in silico target prediction analyses." (PMID 20354523, 2010). "In this study, however, we provide the first evidence of experimental validation that three different miRNAs (let-7f, miR-224, and miR-516a) can target KLK10 (using two distinct approaches) and subsequently have an effect on ovarian cancer cell proliferation." (PMID 20354523, 2010). "In conclusion, our combined bioinformatics and experimental approach provides evidence that KLK10 is a downstream target for multiple miRNAs in ovarian cancer, with a positive proliferative effect on cancer cell proliferation." (PMID 20354523, 2010). "To test the downstream biological effect of miRNAs on KLK10, we measured ovarian cancer cell proliferation." (PMID 20354523, 2010). "KLK6 and KLK10 in particular are highly expressed in ovarian cancer." (PMID 40836974, 2024). "In contrast, KLK10 promoted ovarian cancer cell growth in a recent study." (PMID 28418926, 2017). "However, underscoring the importance of considering tumor-type specific effects, KLK10 has been found to be an unfavorable prognostic indicator in gastric, colorectal and ovarian cancer." (PMID 26231762, 2015). "The vertebrate gene icb-1 previously has been shown to inhibit growth of ovarian cancer cells in vitro and to suppress expression of ovarian cancer biomarkers like kallikrein-related peptidase 10 and claudin 16 or other cancer-related genes activated by estrogens or TNFα." (PMID 24826199, 2014).
ovarian carcinoma (continued). "In an analysis of kallikreins 6, 10, CA125, and hemostatic markers and 5-year survival outcome from epithelial ovarian carcinoma, it was found that ovarian carcinoma patients who lived past 60 months shared similar elevated preoperative levels of KLK10 and CA125 seen among benign cyst patients." (PMID 23319948, 2012). "Results from an ovarian cancer xenograft model suggest that KLK10 has a tumor suppressive function." (PMID 23319948, 2012). "Among these, KLK6, KLK7, KLK8, and KLK10 showed the highest statistical significance in ovarian cancer effusions over other cancer groups, suggesting that these kallikreins might be useful biomarkers in differential diagnosis of ovarian cancer." (PMID 23319948, 2012). "KLK6, KLK10, and KLK11 may provide novel serological diagnostic markers since their expression levels in serum are significantly higher in ovarian cancer patients than in healthy subjects." (PMID 23319948, 2012). "The KLK10 protein was also purified from ascites fluid of ovarian cancer patients." (PMID 20354523, 2010). "Together with published data about potential effect of KLKs on ovarian cancer proliferation, these data strongly suggest that KLK10 is a candidate downstream target by which miRNA can affect ovarian cancer proliferation, although further experimental validation is required." (PMID 20354523, 2010). "Moreover, KLK10 turned out to be a favorable biomarker, e.g., in ovarian cancer." (PMID 36294951, 2022). "The expression of KLK10 is down-regulated in several cancers (e.g. breast, prostate and non-small cell lung cancer, and hepatocellular carcinoma), and up-regulated in colorectal cancer, ovarian cancer, pancreatic ductal adenocarcinoma and uterine papillary serous carcinoma." (PMID 23977389, 2013). "Furthermore, results support the putative role of KLK10 as a tumour suppressor and suggest it may hold therapeutic potential in ovarian cancer." (PMID 22102857, 2011). "In fact, in the present study, we found a positive coregulation of KLK10 and KLK11 in TNBC tissue, a mechanism that has also been described in other cancer entities, such as ovarian cancer." (PMID 36294951, 2022). "In a previous study, we have observed that the combination of the coordinately expressed proteases KLK10 and KLK11 leads to better accuracy in terms of prognostic biomarkers in ovarian cancer than either KLK10 or KLK11 alone." (PMID 33087135, 2020). "Another study showed that seven genes (KLK5-8, KLK10, KLK11, and KLK14) were elevated in ovarian cancer tissue samples and cell lines compared with the healthy ovary." (PMID 33150763, 2020). "Whereas in the normal ovary only KLK10 and to a lesser extent KLK11 and KLK14 are expressed, most of the members of the KLK family are considerably upregulated in ovarian cancer." (PMID 30811511, 2019). "NMA White et al15 confirmed that miR‐516a‐3p can target kallikrein 10 (KLK10) and subsequently affect ovarian cancer cell proliferation." (PMID 31273950, 2019). "It has been reported that at the transcriptional level, KLK4–8, KLK10 and KLK14 are highly expressed in ovarian cancer tissues." (PMID 24043563, 2014). "High protein levels of KLK4–7 and KLK10 have been found in ovarian cancer tissues, while KLK5–8, KLK10, KLK11, KLK13 and KLK14 were found in ascites fluid from ovarian cancer patients as reviewed." (PMID 24043563, 2014). "Recent studies suggested icb-1 to act as a tumor suppressor in ovarian cancer - its knockdown accelerated growth of various ovarian cancer cell lines and led to upregulation of ovarian cancer markers like CLDN16 and KLK10." (PMID 24826199, 2014). "In ovarian cancer, KLK4-KLK8, KLK10 and KLK14 are upregulated and we previously reported that KLK4 and KLK7 were highly expressed in the most lethal histotype, serous EOCs." (PMID 23451143, 2013).